ENSG00000261147 (novel protein)
Gene: Protein-coding gene on chromosome 15 (90,249,556 to 90,272,208, forward strand). Ensembl gene ENSG00000261147.
Genetic constraint (gnomAD): Missense variants: 251 observed, 287.9 expected, observed/expected ratio (o/e) 0.87, 90% interval 0.79 to 0.97. Synonymous variants: 85 observed, 104.72 expected, observed/expected ratio (o/e) 0.81, 90% interval 0.68 to 0.97.